PMP2 (peripheral myelin protein 2)
Description:
May play a role in lipid transport protein in Schwann cells. May bind cholesterol.
Synonyms: MP2; FABP8; M-FABP; CMT1G; P2
Tractability: Small molecule: a structure with a bound ligand is known; it has a binding pocket of medium quality.
Gene: Protein-coding gene on chromosome 8 (81,440,326 to 81,447,518, reverse strand). Ensembl gene ENSG00000147588.
Subcellular location: Cytoplasm
Gene Ontology:
Molecular function: cholesterol binding; fatty acid binding; protein binding; lipid binding
Biological process: fatty acid transport; membrane organization
Cellular component: extracellular exosome; cytosol; nucleus; cytoplasm; myelin sheath
Genetic constraint (gnomAD): Loss-of-function variants: 6 observed, 7.71 expected, observed/expected ratio (o/e) 0.78, 90% interval 0.43 to 1.51. That is too few expected variants to judge how well the gene tolerates losing a copy. Missense variants: 106 observed, 102.83 expected, observed/expected ratio (o/e) 1.03, 90% interval 0.88 to 1.21. Synonymous variants: 36 observed, 38.44 expected, observed/expected ratio (o/e) 0.94, 90% interval 0.72 to 1.24.
Gene-disease validity (ClinGen):
ClinGen rates the evidence that PMP2 causes each of these diseases.
Charcot-Marie-Tooth disease (autosomal dominant): Moderate. An inherited degenerative disorder involving the peripheral nerves.
Homologues: Orthologues: chimpanzee PMP2 (100% identical), macaque PMP2 (98% identical), dog PMP2 (94% identical), pig PMP2 (94% identical), guinea pig PMP2 (92% identical), rat Pmp2 (90% identical), mouse Pmp2 (87% identical), zebrafish fabp4a (52% identical), zebrafish fabp4b (48% identical), Drosophila melanogaster fabp (45% identical), Caenorhabditis elegans lbp-7 (41% identical), zebrafish rbp7a (37% identical), and 2 more. Paralogues in human: FABP9 (67% identical), FABP4 (67% identical), FABP12 (66% identical), FABP3 (63% identical), FABP7 (59% identical), FABP5 (55% identical), CRABP1 (39% identical), RBP1 (38% identical), RBP2 (38% identical), RBP7 (38% identical), CRABP2 (35% identical), RBP5 (35% identical), and 3 more.
Diseases named in the same sentence as PMP2 in open-access papers:
PMP2 is named in the same sentence as 21 diseases in open-access papers, as found by Europe PMC text mining. Sharing a sentence is not in itself a finding about the gene and the disease. The quoted sentences say what the papers report.
melanoma (7 papers, 2020 to 2025). A malignant, usually aggressive tumor composed of atypical, neoplastic melanocytes. "FABP8 (PMP2) has been shown to be associated with melanoma invasion." (PMID 33352874, 2020). "Another study showed that PMP2 expression in melanoma cells is regulated by the transcription factor SOX10 and is linked to melanoma cell invasivenes." (PMID 40538623, 2025). "Further, both genes with increased expression in intracranial metastases (PMP2 and GLDN) have known associations with melanoma cell invasion and mutation." (PMID 38671536, 2024). "All others demonstrate an increased expression in melanoma development, some even strongly like PMP2 (5.7-fold), TNC (10.2-fold), MMP1 (65.6-fold), and CDH2 (10.2-fold)." (PMID 34439267, 2021). "Studies indicate that PMP2 expression enhances the invasive capacity of melanoma cells." (PMID 40717587, 2025). "The myelin protein PMP2 is involved in the regulation of melanoma cell invasion and may present a novel therapeutic target." (PMID 38671536, 2024). "However, PMP2 protein expression is only detected in certain melanoma cell lines, which may reflect the heterogeneity of melanoma." (PMID 40717587, 2025). "However, SOX10 can also promote invasion by upregulating its direct target genes melanoma inhibitory activity (MIA) and peripheral myelin protein 2 (PMP2)." (PMID 34071193, 2021).
neurofibroma (2 papers, 2023). An intraneural or extraneural neoplasm arising from nerve tissues and neural sheaths. "Neurofibroma tumor nuclei remain most similar to Schwann cells, with expression of markers such as S100B, PMP2, MPZ and ERBB3." (PMID 37164978, 2023).
neuropathy (2 papers, 2016 to 2019). A disorder affecting the nervous system that manifests with pain, tingling, numbness, and/or muscle weakness. "For clear demonstration of PMP2 mutation-associated neuropathy, further studies using knock-in mouse models are needed." (PMID 26828946, 2016). "Importantly, we expand the clinical and electrophysiological spectrum of PMP2-related neuropathy with the identification of very mildly affected individuals who have only subtle proximal demyelination and focal pattern of distribution along peripheral nerves." (PMID 31412900, 2019).
amyotrophic lateral sclerosis (1 paper, 2023). Amyotrophic lateral sclerosis (ALS) is a neurodegenerative disease characterized by progressive muscular paralysis reflecting degeneration of motor neurons in the primary motor cortex, corticospinal tracts, brainstem and spinal cord. "Correspondingly, the numbers of the Pmp2+ SCs are reduced in amyotrophic lateral sclerosis (ALS) SOD1G93A mouse model as well as human ALS nerve samples." (PMID 36998728, 2023).
asthma (1 paper, 2018). "Furthermore, the expression levels of the known IRE1α–RIDD target genes Hqsnat, Blos1, Scara3, Pdqfrb, Pmp2 and Col6 were decreased in OVA/LPS-induced asthma and recovered with IC87114 administration." (PMID 29504610, 2018).
delirium (1 paper, 2018). A disorder characterized by confusion; inattentiveness; disorientation; illusions; hallucinations; agitation; and in some instances autonomic nervous system overactivity. "Five proteins (CHI3L1, IL6, SFRP2, PMP2, and RTN4R) differed in serum in patients with postoperative delirium compared to baseline with corrected p < 0.01 and 11 at p < 0.05." (PMID 30367354, 2018).
demyelinating polyneuropathy (1 paper, 2019). Polyneuropathy that is characterized by demyelination of axons. "Nerve conduction studies of the PMP2 patients reported up to now demonstrate classical features of demyelinating polyneuropathy with very slow CVs of the motor and sensory nerves below 20 m/s and secondary axonal degeneration." (PMID 31412900, 2019).
glioma (1 paper, 2020). A benign or malignant brain and spinal cord tumor that arises from glial cells (astrocytes, oligodendrocytes, ependymal cells). "We included into the custom set three probes for genes expressed in glioma tumors (GFAP, OLIG2 and PMP2), in addition to the CNS HGNET-BCOR marker probes, and performed hybridization in the series of 27 tumors originally diagnosed as HGG and one HGG relapsed sample." (PMID 32650833, 2020).
myeloma (1 paper, 2023). "We selected genes (ARHGAP26, MYH10, PMP2, RFX8, BAMBI, CLEC12b) with significant changes in methylation level to validate their expression using qRT-PCR in U266 myeloma cells." (PMID 38201971, 2023).
ovarian carcinoma (1 paper, 2025). A malignant neoplasm originating from the surface ovarian epithelium. "FABP8 (PMP2) has been identified as a potential blood-based biomarker for ovarian cancer." (PMID 40717587, 2025).
schwannoma (1 paper, 2025). A benign, usually encapsulated slow growing tumor composed of Schwann cells. "FABP8 (PMP2) exhibits a specific expression pattern in schwannomas." (PMID 40717587, 2025). "Aberrant PMP2 expression may contribute to schwannoma development." (PMID 40717587, 2025).
cancer (5 papers, 2020 to 2025). A tumor composed of atypical neoplastic, often pleomorphic cells that invade other tissues. "Metabolomic and proteomic analyses suggest that PMP2 is associated with cancer plasticity and signaling pathways, potentially offering a new target for early diagnosis." (PMID 40717587, 2025). "The downregulated genes TNC and MMP1 are known to be commonly induced in cancer, the same is true for PMP2 and CDH2." (PMID 34439267, 2021). "The carnitine system is related to cancer metabolic plasticity and acetylation of carnitine facilitates myelination of regenerated axons after peripheral nerve injuries with physical binding to PMP2 and TUBB." (PMID 33228226, 2020). "Especially, through this analysis, proteins (PPCS, PMP2, and TUBB) and metabolites (L-carnitine and PC-O (30:0)) related to the carnitine system involved in cancer plasticity were identified." (PMID 33228226, 2020).
peripheral neuropathy (4 papers, 2016 to 2022). A disorder affecting the peripheral nervous system. "The PMP2 gene causes – when mutated – the peripheral neuropathy Charcot–Marie–Tooth (CMT) disease type 1G." (PMID 35543322, 2022). "We expand the genetic and phenotypic spectrum of PMP2-related peripheral neuropathy." (PMID 31412900, 2019). "For instance, decreases in PMP2, whose mutations can cause demyelinating Charcot–Marie–Tooth disease (CMT) is sufficient to modify the lipidome of peripheral myelin, while heterozygous loss of Pmp22, causing human peripheral neuropathy, disrupts myelin junctions in mice." (PMID 28243725, 2017).
tumor (4 papers, 2022 to 2025). "To summarize, our findings demonstrate that PMP2 plays a role in inhibiting tumor metastasis during EOCRC tumorigenesis." (PMID 40538623, 2025). "Further, qRT-PCR and IHC highlighted that PMP2 was downregulated in EOCRC tumor tissues compared to normal tissues." (PMID 40538623, 2025). "Additionally, PMP2 knockdown significantly enhanced the migration and invasion capabilities of HCT116 and LOVO cells, indicating that PMP2 may function as a suppressor of tumor metastasis during EOCRC progression." (PMID 40538623, 2025).
infection (2 papers, 2014 to 2022). The state of being infected such as from the introduction of a foreign agent such as serum, vaccine, antigenic substance or organism. "Previous studies reported that PMP2 is expressed in humans but not in mouse astrocytes; infection of mouse astrocytes with a PMP2-expressing virus increased the cell diameter and number of primary processes." (PMID 36274991, 2022).
PMP2 also shares sentences with these, for which no sentence is quoted: Charcot-Marie-Tooth disease (2 papers); Charcot-Marie-Tooth Neuropathy (2); hepatocellular carcinoma (2); anaplastic oligodendroglioma (1); colorectal cancer (1); motor neuron disease (1).